RN7SL708P (RNA, 7SL, cytoplasmic 708, pseudogene)
Gene: Miscellaneous RNA gene on chromosome 19 (49,081,332 to 49,081,630, forward strand). Ensembl gene ENSG00000265675.
Homologues: Orthologues: macaque Metazoa_SRP (92% identical), dog Metazoa_SRP (68% identical). Paralogues in human: RN7SL2 (82% identical), RN7SL1 (81% identical), RN7SL3 (80% identical), RN7SL660P (79% identical), RN7SL788P (79% identical), RN7SL11P (79% identical), RN7SL566P (79% identical), RN7SL732P (79% identical), RN7SL177P (78% identical), RN7SL220P (78% identical), RN7SL333P (78% identical), RN7SL712P (78% identical), and 700 more.